CCL24 (C-C motif chemokine ligand 24)
Diseases named in the same sentence as CCL24 in open-access papers (continued):
Sharing a sentence is not in itself a finding about the gene and the disease.
parasitic infections (3 papers, 2012 to 2023). "CCL24 is a specific agonist for CCR3, attracting and activating eosinophils in parasitic diseases." (PMID 22506080, 2012).
skin inflammation (3 papers, 2017 to 2020). "The expression of CCL24 was more consistently and strongly increased compared with CCL11 in the skin of mutant mice suggesting a more important role for CCL24 in the dermatitis of SHARPIN-deficient mice." (PMID 32687504, 2020). "As well as highlighting that Hh-mediated transcription in T cells promotes TGF-β signaling to dampen skin inflammation, our RNA-seq of CD4+ T cells from AD skin showed that Hh reduced expression of Ccl24 and Ccl8, and these chemokines recruit eosinophils to the skin." (PMID 31264977, 2019).
Stroke (3 papers, 2024). Sudden impairment of blood flow to a part of the brain due to occlusion or rupture of an artery to the brain. "Genes related to inflammation such as Ccl5, Cxcl5, Il1a, Tnfsf10, Nfkb1, Tnfrsf1b, Ccr7, Tnfrsf9, Ccl7, Il1b, Il6, and Ccl24 were also downregulated upon MMP-3 KO in male stroke brains." (PMID 39000490, 2024). "The expression of ligands for CCR3, CCL5, CCL11 and CCL24, have been studied in stroke models." (PMID 38332938, 2024). "In addition, CCR3 ligand CCL24 is a biomarker for AMD and could be similarly explored as a biomarker for VCID and other stroke outcomes." (PMID 38332938, 2024).
viral infection (3 papers, 2018 to 2023). "In mild persistent asthmatics, viral infection was associated with increased protein abundance of CXCL10, sICAM-1, CCL2, CCL4, CCL5, CCL20 and CCL24." (PMID 30463560, 2018). "In moderate-to-severe persistent asthmatics, viral infection was associated with increased protein abundance of CXCL10, IL-4, sICAM-1, CCL2, CCL20 and CCL24." (PMID 30463560, 2018). "For FVC, statistically significant interactions between viral infection and inflammation were seen for CXCL10 mRNA, TLR3 mRNA, IL-4, IL-13, CCL5, CCL20 and CCL24." (PMID 30463560, 2018). "For FEV1, statistically significant interactions between viral infection and inflammation were seen for CXCL10 and TLR3 mRNA, IL-4 and CCL24 levels." (PMID 30463560, 2018). "For example, in the absence of viral infection, CXCL10 mRNA, MDA5 mRNA, CXCL10, IL-4, IL-13, CCL4, CCL5, CCL20 and CCL24 were negatively associated with FVC." (PMID 30463560, 2018). "In our longitudinal study, we found that, in the absence of viral infection, CXCL10, IL-4, IL-13, CCL4, CCL5, CCL20 and CCL24 were each negatively associated with FVC." (PMID 30463560, 2018).
airway allergy (2 papers, 2017). "Indeed, the coexpression of Ccl11 and Ccl24,45 or IL-5 and Ccl24,46 correlates with persistent airway eosinophilia in mice with severe airway allergy." (PMID 27484038, 2017). "Furthermore, blocking Ccl24 in vivo abrogated the exacerbated airway inflammation induced by TPL-2–deficient DCs, demonstrating a previously unappreciated role for DC-intrinsic TPL-2 in regulating Ccl24 to limit severe airway allergy." (PMID 27484038, 2017). "Consistent with this hypothesis, severe airway allergy induced by adoptive transfer of Map3k8−/− DCs could be blocked by neutralization of Ccl24." (PMID 27484038, 2017).
Arthritis (2 papers, 2018 to 2021). Inflammation of a joint. "Despite the different results among research, these results highlighted that the CCL24, as a biomarker of this model, may be vital proteins or peptides that participate in the pathogenesis of RA and may be a promising potential therapeutic target for arthritis." (PMID 33718399, 2021).
atherosclerosis (2 papers, 2022 to 2023). A disease characterized by the build-up of fatty material and calcium deposition in the arterial wall resulting in partial or complete occlusion of the arterial lumen. "This is in line with previous findings showing that CCL24 is involved in the initiation and progression of atherosclerosis and VSMC calcification." (PMID 35159221, 2022). "LYVE-1 macrophages have been shown to regulate arterial stiffness by controlling collagen expression in VSMCs and they express a high level of CCL24 (eotaxin-2), a chemokine shown to promote atherosclerosis damage and VSMC calcification." (PMID 35159221, 2022). "CCL24 has been shown to play a role in the initiation and progression of atherosclerosis and VSMC calcification." (PMID 35159221, 2022). "Targeting circulating CCL24 in atherosclerosis with CM-101 may prove to be a novel approach to not only reduce inflammation and vascular calcification, but to also have beneficial effects on plaque stability, reducing cardiovascular events." (PMID 35159221, 2022). "We identified an atherosclerosis-associated LYVE-1+ res-like macrophage population via RNAseq analysis, which was found to trigger VSMC transdifferentiation to osteoblast/chondrocyte-like cells, in a CCL24-dependent manner." (PMID 35159221, 2022). "Extending mechanistic investigations on CCL24 may raise enticing therapeutic opportunities for abrogating the transdifferentiation of VSMCs into osteoblast/chondrocyte-like cells to prevent vascular calcification in atherosclerosis." (PMID 35159221, 2022).
cholestasis (2 papers, 2023 to 2024). Impairment of the bile flow caused by obstruction within the liver, or outside the liver in the bile duct system. "The cholestasis/inflammatory/fibrotic reaction is perpetuated by a positive feedback loop that further sustains the elevation of CCL24 in the injury sites." (PMID 37345655, 2023). "CCL24-neutralizing monoclonal antibody, CM-101, significantly improved inflammation, fibrosis, and cholestasis-related markers in the biliary area." (PMID 37345655, 2023). "Additionally, we showed the therapeutic potential of CCL24 blockade in a preclinical cholestasis model." (PMID 38334601, 2024). "Our data support CCL24 as regulator/mediator of the cholestasis/inflammatory/fibrotic axis." (PMID 37345655, 2023). "Treatment with CM-101, a CCL24-neutralizing antibody, in an α-naphthylisothiocyanate (ANIT)-induced cholestasis mouse model effectively inhibited accumulation of peribiliary neutrophils and macrophages while reducing biliary hyperplasia and fibrosis." (PMID 38334601, 2024).
Cirrhosis (2 papers, 2024 to 2025). A chronic disorder of the liver in which liver tissue becomes scarred and is partially replaced by regenerative nodules and fibrotic tissue resulting in loss of liver function. "ROC curves show that these metrics and CCL24 are associated with the presence of cirrhosis." (PMID 38892228, 2024). "In patients with PSC, CCL24 serum levels correlate with fibrotic markers, and distinctly higher CCL24 levels are observed in patients with cirrhosis." (PMID 39851534, 2025). "Machine learning applied to broad proteomic profiling of sera allowed for the discovery of markers of disease presence, severity, and cirrhosis and the exploration of the involvement of CCL24, a chemokine with fibro-inflammatory activity." (PMID 38892228, 2024). "This is consistent with a previous report of increased CCL24 levels in hepatitis B patients who developed cirrhosis." (PMID 38892228, 2024). "Finally, patients exhibiting elevated CCL24 levels were observed to have an increased probability of developing cirrhosis, as demonstrated by the Kaplan–Meier curve analysis." (PMID 38892228, 2024). "However, proteins that correlated with the development of cirrhosis, such as CCL24, are not biomarkers per se, but their elevated levels indicate a role in disease pathogenesis." (PMID 38892228, 2024). "Furthermore, when comparing patients who did not develop cirrhosis to those who were already cirrhotic at the time serum was taken and to patients who developed cirrhosis after sampling, significant differences are shown for platelets (PLT) and CCL24." (PMID 38892228, 2024).
cognitive decline (2 papers, 2023 to 2024). "Increased expression of CCR3 and its ligands (CCL5, CCL11, and CCL24) are also associated with cognitive decline associated with aging." (PMID 38332938, 2024).
cognitive deficits (2 papers, 2023). "To further assess a critical role for CCR3, we tested CCL24, another ligand which increases with age, and found that administration of recombinant CCL24 also induced cognitive deficits." (PMID 36934154, 2023).
cutaneous leishmaniasis (2 papers, 2023). Leishmaniasis affecting the skin. "In summary, we demonstrate that dermal TRMs orchestrate localized type 2 circuitries with ILC2s and eosinophils, mediated by TSLP and CCL24 respectively, to promote non-healing cutaneous leishmaniasis." (PMID 38030609, 2023). "Here Lee and colleagues show dermis-resident macrophages are a source of thymic stromal lymphopoietin and CCL24, which act on type 2 innate lymphoid cells and eosinophils respectively, to maintain their M2 properties and promote non-healing cutaneous leishmaniasis." (PMID 38030609, 2023).
eosinophilic esophagitis (2 papers, 2016 to 2017). Eosinophilic esophagitis (EoE) is a chronic, allergic disease of the esophagus characterized clinically by symptoms of esophageal dysfunction (including vomiting, dysphagia, feeding disorders, food impaction and abdominal pain) which persist after treatment with proton pump inhibitors (PPIs). "Besides, IL-13 has been implicated in inflammation and remodeling by inducing chemokines (CCL-3, CCL-4, CCL-5 and CXCL-1), and IL-13 is a direct inducer of both CCL11 and CCL24 in eosinophilic esophagitis." (PMID 27533463, 2016).
helminth infections (2 papers, 2013 to 2025). "Elevated Eotaxin-2/CCL24 levels have been found in experimental helminth infections and in acutely infected S. mansoni patients, and high Eotaxin-2/CCL24 levels were associated with increased liver damage in S. mansoni-infected mice." (PMID 23855879, 2013).
metabolic dysfunction-associated steatohepatitis (2 papers, 2023 to 2025). Metabolic dysfunction-associated steatohepatitis (MASH, formerly known as nonalcoholic steatohepatitis or NASH) is a type of fatty liver disease. "In liver biopsies from patients with nonalcoholic steatohepatitis (NASH) and hepatocellular carcinoma, both CCR3 and CCL24 were found to be hyperexpressed, and high CCR3 expression in hepatic fibroblasts was demonstrated in both liver diseases." (PMID 37345655, 2023).
neurosyphilis (2 papers, 2020 to 2023). Infection of the brain or spinal cord by Treponema pallidum. "Increased CCL24 and CXCL7 expression was seen throughout all neurosyphilis stages, had moderate diagnostic efficiency for neurosyphilis, and correlated poorly with CSF cell count and Venereal Disease Research Laboratory titer." (PMID 32419252, 2020). "Meanwhile, the increased levels of CXCL9, CXCL7, CCL24, IL-17, IL-26, and migration inhibitory factor (MIF) of macrophages in the CSF of neurosyphilis patients suggested their role as promising differential diagnostic tools for neurosyphilis." (PMID 38105236, 2023). "The increased CSF levels of CCL24, CXCL7, and CXCL8 require further investigation to elucidate the role of eosinophils and neutrophils in neurosyphilis." (PMID 32419252, 2020). "The levels of CCL24 (P = .0185), CXCL7 (P < .0001), CXCL13 (P < .0001), CXCL10 (P < .0001), and CXCL8 (P < .0001) in the CSF of neurosyphilis patients were higher than those in the CSF of patients without neurosyphilis." (PMID 32419252, 2020). "Our data are consistent with those of Wang et al8; additionally, our study identified that CCL24 and CXCL7 levels are increased in the CSF of patients with neurosyphilis." (PMID 32419252, 2020). "ELISA confirmed significantly higher CCL24 and CXCL7 levels in the CSF of patients with than without neurosyphilis (CCL24: 6.082 ± 1.137 pg/mL vs 1.773 ± 0.4565 pg/mL, P = .0037; CXCL7: 664.3 ± 73.19 pg/mL vs 431.1 ± 90.54 pg/mL, P = .0118)." (PMID 32419252, 2020). "Using ROC curve analysis, we showed that CSF and serum CCL24 and CXCL7 levels have moderate diagnostic performance for neurosyphilis, although they are not quite suitable as biomarkers for discriminating neurosyphilis from non‐neurosyphilis, given their sensitivity and specificity values." (PMID 32419252, 2020). "However, no previous reports have described changes in serum and CSF CCL24 levels in patients with neurosyphilis; we demonstrated higher CSF levels of CCL24, independently of serum levels, in these patients than in those with non‐neurosyphilis." (PMID 32419252, 2020). "The CSF levels of CCL24 and CXCL7 were both statistically significantly higher in patients with neurosyphilis than in those without (CCL24: 6.082 ± 1.137 pg/mL vs 1.773 ± 0.4565 pg/mL, P = .0037; CXCL7: 664.3 ± 73.19 pg/mL vs 431.1 ± 90.54 pg/mL, P = .0118)." (PMID 32419252, 2020). "We found that the levels of CXCL13, CCL24, CXCL8, CXCL10, and CXCL7 were significantly higher in the CSF of those with than those without neurosyphilis." (PMID 32419252, 2020). "We then validated whether the levels of CCL24 and CXCL7 were elevated in the CSF of patients with neurosyphilis, as compared to the levels in those without neurosyphilis, by performing ELISA measurements." (PMID 32419252, 2020). "Moreover, the CSF levels of CCL24 and CXCL7 were not different among different stages of neurosyphilis." (PMID 32419252, 2020). "Antibody array analysis showed that the CSF levels of CCL24 (P = .0185), CXCL7 (P < .0001), CXCL13 (P < .0001), CXCL10 (P < .0001), and CXCL8 (P < .0001) were significantly higher in patients with than without neurosyphilis." (PMID 32419252, 2020).
Obesity (2 papers, 2020 to 2021). Accumulation of substantial excess body fat. "Furthermore, the expression of chemokine signaling molecules, including CCL24, CCR6, and CXCR3, was altered in accordance with female-specific fluctuations in VAT-Treg in obesity." (PMID 32240221, 2020).
pneumonia (2 papers, 2023 to 2024). An acute, acute and chronic, or chronic inflammation focally or diffusely affecting the lung parenchyma, caused by an infection in one or both of the lungs (by bacteria, viruses, fungi, or mycoplasma.). "Specifically, FOXM1 can affect inflammation in pneumonia through NF-κB and the JAK/STAT signaling pathway and FOXM1 deficiency reduces the expressions of CCL11, CCL24 and chemokine receptors CCR2 and CX3CR1 to further affect inflammation." (PMID 36964598, 2023).
preeclampsia (2 papers, 2014 to 2023). Preeclampsia is a hypertensive disorder of pregnancy that is characterized by new-onset hypertension with proteinuria presenting after 20 weeks of gestation, and depending on mild or severe forms may initially present with severe headache, visual disturbances, and hyperreflexia. "Furthermore, umbilical artery chemokine CCL16 and CCL24 levels were significantly higher in preeclampsia cords." (PMID 25485631, 2014).
acute promyelocytic leukemia (1 paper, 2020). An aggressive form of acute myeloid leukemia (AML), characterized by arrest of leukocyte differentiation at the promyelocyte stage, due to a specific chromosomal translocation t(15;17) in myeloid cells. "In addition, CCL24 is involved in acute promyelocytic leukemia (APL), and differentiation therapy with all-trans retinoic acid induces CCL24 production in the lung and APL cells, both of which trigger the migration of leukemic cells." (PMID 32051393, 2020).
age-related macular degeneration (1 paper, 2017). Age-related loss of vision in the central portion of the retina (macula), secondary to retinal degeneration. "Since CCL24 was investigated to accelerate neovascularization in age-related macular degeneration (AMD), we explored the effect of CCL24 on tube formation." (PMID 28042950, 2017).
allergic conjunctivitis (1 paper, 2023). "In 2020, Shoji demonstrated that tear levels of CCL17/TARC, CCL24/eotaxin-2, and IL-16 in VKC and AKC patients were significantly higher than in patients with other allergic conjunctivitis, like SAC and PAC (p < 0.01)." (PMID 37658939, 2023).
anemia (1 paper, 2023). A reduction in the number of red blood cells, the amount of hemoglobin, and/or the volume of packed red blood cells. "Interestingly, the increase in CXCL-13 was accompanied by decrease in CCL-24, suggesting opposing roles for these two chemokines in PM-associated anemia." (PMID 36689438, 2023). "Only CXCL-13 and CCL-24 in both peripheral (p = 0.01 and <0.0001, respectively) and placental (p = 0.01 and p = 0.02, respectively) plasma were associated significantly with maternal anemia in PM+ women when compared to the healthy controls." (PMID 36689438, 2023).
atrial fibrillation (1 paper, 2023). A disorder characterized by an electrocardiographic finding of a supraventricular arrhythmia characterized by the replacement of consistent P waves by rapid oscillations or fibrillatory waves that vary in size, shape and timing and are accompanied by an irregular ventricular response. "In our study, the CCL24 blocking antibody could reduce the incidence and duration of atrial fibrillation; in mechanism, we found that the CCL24-neutralizing antibody recovers the APD80 of mice’s right atrium during Ang II stimulation." (PMID 36131165, 2023). "Epicardium electrical stimulation induced atrial fibrillation/atrial flutter (AF/AFL) in 83.3% of Ang II–induced mice, but rarely in CCL24 Ab mice." (PMID 36131165, 2023).
bipolar disorder (1 paper, 2018). A disorder of the brain that causes unusual shifts in mood, energy, activity levels and the ability to carry out day-to-day tasks. "Taking into account that IP-10/CXCL10 is associated with a Th1 response, and eotaxin-2/CCL24 (as eotaxin-1/CCL11) is related to a Th2 response, this result suggested an imbalance of Th1/Th2 cytokines toward a Th1 profile in bipolar disorder." (PMID 29962972, 2018). "Patients with bipolar disorder showed increased levels of IP-10/CXCL10, lower levels of eotaxin-2/CCL24 and similar levels of the other chemokines compared to controls." (PMID 29962972, 2018). "Soon after, we evaluated the serum levels of a set of chemokines (CCL2, CCL3, CCL11, CCL24, CXCL8, CXCL9, CXCL10) in 30 euthymic patients with bipolar disorder and 30 matched controls." (PMID 29962972, 2018).
bladder tumor (1 paper, 2021). "Similarly, MMPs 7, 10 and 13 are involved in bladder tumor growth and metastasis and CCL24 is implicated in angiogenesis, thus reduction in expression of these genes would be consistent with tumor reduction." (PMID 34944584, 2021).
breast carcinoma (1 paper, 2021). "Both IL-28A and SCF produce antitumor effects, and higher levels of CCL24 improve prognosis in breast cancer." (PMID 34575976, 2021).
calcification (1 paper, 2022). Process by which organic tissue becomes hardened by the physiologic deposit of calcium salts. "Furthermore, symptomatic CAD patients exhibited a higher systemic level of CCL24 in comparison to asymptomatic patients, which also correlated positively with the extent of vascular calcification." (PMID 35159221, 2022).
cardiac hypertrophy (1 paper, 2023). "Moreover, CCL24 expression was significantly reduced in the treatment of TAC-induced cardiac hypertrophy and heart failure with sodium-glucose co-transporter 2 inhibitors (TD139)." (PMID 36131165, 2023).
cerebral malaria (1 paper, 2023). A sequestration of Plasmodium falciparum in the brain, which can cause coma and/or seizures. "This discrepancy might be explained by differences in the immuno-pathogenesis mechanisms of placental and cerebral malaria that include the differential expression of certain cytokines including CXCL4 and CCL24." (PMID 36689438, 2023).
cholangitis (1 paper, 2023). An acute or chronic inflammatory process affecting the biliary tract. "Finally, we corroborated the effect of blocking CCL24 in an additional cholangitis model." (PMID 37345655, 2023).